ACE (angiotensin I converting enzyme)
Diseases named in the same sentence as ACE in open-access papers (continued):
Sharing a sentence is not in itself a finding about the gene and the disease.
Hypertension (continued). "In Japanese individuals with T2DM, hypertension, and microalbuminuria, the administration of esaxerenone in combination with an angiotensin-converting enzyme inhibitor (ACE-i) or angiotensin II receptor blocker (ARB) has been shown to increase the rate of reduction or remission of albuminuria." (PMID 39318608, 2024). "Consistent with the use of RAS inhibitors, such as ACE inhibitors and angiotensin receptor blockers (ARBs), which are widely prescribed for the treatment of hypertension, our data demonstrate that inhibition of the classic RAS by STS-loaded NPs is associated with a BP-lowering effect." (PMID 39765901, 2024). "Future research could explore genetic variations related to ACE and hypertension to tailor recommendations for sourdough bread consumption." (PMID 39125261, 2024). "Inhibitors of the renin–angiotensin–aldosterone system (RAAS), such as ACE inhibitors (ACEi), angiotensin-II receptor blockers and mineralocorticoid receptor antagonists, reduce morbidity and mortality in hypertension, congestive heart failure and chronic kidney disease." (PMID 39708241, 2024). "The five principal classes of antihypertensive drugs, including calcium antagonists, β-blockers, angiotensin-converting enzyme (ACE) inhibitors, thiazide diuretics, and angiotensin receptor blockers, are widely recognized for their efficacy in long-term management of hypertension." (PMID 38766523, 2024). "Therefore, P. minor holds potential as a natural source of ACE inhibitors for the prevention and complementary treatment of hypertension." (PMID 39598284, 2024). "Angiotensin-converting enzyme (ACE) plays a crucial role in the pathogenesis of hypertension." (PMID 38474055, 2024). "Pharmacological interventions lower blood pressure (BP) by inhibiting the renin-angiotensin-aldosterone system (RAAS), such as angiotensin-converting enzyme (ACE) inhibitors, have long been proven effective in clinical and experimental settings for the treatment of hypertension and HF." (PMID 39355349, 2024). "Currently, hypertension can be treated with a variety of synthetic angiotensin-converting enzyme (ACE) inhibitors, another enzyme that affects vascular function, either by converting angiotensin I to angiotensin II, which causes vasoconstriction, or by degrading bradykinin, a potent vasodilator." (PMID 38892529, 2024). "ACE inhibitors, used to manage hypertension, may result in a persistent dry cough, elevated blood potassium levels, low blood pressure, and kidney impairment." (PMID 39273041, 2024). "This dual mechanism—enhancing NO production and inhibiting ACE—could provide a comprehensive approach to managing hypertension and improving vascular health." (PMID 39590851, 2024). "The polyphenolic compounds in SB may inhibit ACE activity, like the mechanism of action observed in ACE inhibitors used to treat hypertension." (PMID 39590851, 2024). "Consequently, ACE inhibitors have emerged as the primary pharmacological agents for hypertension treatment." (PMID 38472752, 2024). "In contrast, patients with hypertension from an endemic region treated with ACE inhibitors may replenish iron pools due to the downregulatory effect of ACE inhibitors on hepcidin expression." (PMID 39885837, 2024). "In conditions of arterial hypertension, this balance is lost in favor of the production of ACE." (PMID 39062156, 2024). "Therefore, CCBs are typically used in combination with anti-hypertensive drugs of another class, such as ACE inhibitors or ARBs, when it comes to treating refractory hypertension." (PMID 39057019, 2024). "Antihypertensive medications used to treat arterial hypertension in our cohort included ß-blockers (n = 57), ACE-inhibitors (n = 9), diuretics (n = 46), calcium-channel-blockers (n = 9), and ⍺1-adrenoreceptor-antagonists (n = 4), including therapy with multiple agents." (PMID 38581464, 2024). "Furthermore, maternal diabetes resulted in hypertension in the offspring, accompanied by an elevation in ACE activity." (PMID 38542273, 2024).
Hypertension (continued). "Captopril is an ACE inhibitor widely used to treat patients with hypertension." (PMID 38333456, 2024). "Given this, ACE and renin inhibition stands as one of the strategies in hypertension treatment." (PMID 39000571, 2024). "Moreover, this peptide led to a decrease in serum ACE activity, further supporting its potential in managing hypertension." (PMID 39452857, 2024). "Our results may be influenced by the fact that a significant proportion of patients had hypertension (23 vs. 0; p<0.001), and 13% of the patients were undergoing ACE inhibitor or ARB treatment." (PMID 39081789, 2024). "Similarly, ACE, in addition to hypertension, is involved in several other renal diseases, such as diabetic kidney disease and acute kidney injury, even when blood pressure is normal." (PMID 38255922, 2024). "Propensity score was used to 1:1 match for age, sex, ischaemic heart disease, hypertension, microvascular complications, chronic kidney disease, HbA1c, BMI and use of pioglitazone, lipid modifying agents, antilipemic agents, ACE inhibitors, angiotensin II inhibitors and metformin." (PMID 38584180, 2024). "Emphasis is given to natural marine ACE inhibitors as alternatives to synthetic drugs to avoid several serious side effects, as they hold significant potential to become newly emerging therapeutic options for the treatment of hypertension." (PMID 39590800, 2024). "Therefore, the study results oppose the well‐known proposal that the beneficial actions of ACEi in hypertension rely upon the patient's ACE activity, and consequently on the type of ACE I/D genotype." (PMID 38924381, 2024). "In addition, studies have shed light on the role of ACE enzyme and its correlation with dyslipidemia, implicating this enzyme’s role in early hypertension and dyslipidemia incidence." (PMID 38961394, 2024). "Microalgae-derived peptides with antioxidative and anti-inflammatory properties may alleviate hypertension and regulate dyslipidemia by inhibiting angiotensin-converting enzyme (ACE) and endothelial nitric oxide synthase 148,149." (PMID 39267781, 2024). "RDN at the early stage of hypertension reduced both fat mass and adipocyte size in the present study, and these changes were accompanied by the downregulation of angiotensinogen and ACE gene expression, suggesting that RDN at this stage suppressed RAS-induced adipocyte growth." (PMID 38355818, 2024). "A slight ACE inhibitory activity was observed, so that the rachis of the pacaya palm could be used as a supportive therapy in the treatment of hypertension, especially the extracts obtained from the rachis subjected to a wet thermal treatment." (PMID 38337933, 2024). "Our centre’s approach to antihypertensive therapy involves calcium channel blockers first-line followed by beta-blockers, then alpha-blockers, then diuretics, and if patients still had uncontrolled hypertension, the use of ACE inhibitors and angiotensin-receptor blockers was carefully considered." (PMID 37658875, 2024). "In addition, different classes of medications, like angiotensin-converting enzyme (ACE) inhibitors and angiotensin-II receptor blockers (ARBs), are used to control hypertension and are associated with cardioprotective properties." (PMID 38994977, 2024). "Results from our study would indicate that hypertension increases stem cell maturity to form endothelial cells and ACE inhibitors may also have an effect of increasing stem cell numbers and maturation." (PMID 39186241, 2024). "ACE inhibition is a preventive alternative to the occurrence of hypertension via vasoconstriction." (PMID 38397511, 2024). "Especially RAS-modifying drugs that are commonly prescribed for the therapy of arterial hypertension might have had an impact on levels of ACE+ or ACE2+ EVs." (PMID 38397093, 2024). "Similarly, ACE inhibitors have demonstrated the ability to enhance arterial properties in hypertension patients." (PMID 39044238, 2024).
Hypertension (continued). "Additionally, ACE inhibitors are considered promising for the treatment of hypertension and related conditions." (PMID 39195461, 2024). "ACE inhibitors are prescribed for uncomplicated hypertension and are also recommended for conditions such as hypertension with concurrent CAD (including post-myocardial infarction), chronic kidney disease (CKD), type 2 diabetes, heart failure with reduced ejection fraction, or atrial fibrillation." (PMID 39330868, 2024). "Therefore, the antioxidant effect of ACE inhibitors contributes to the prevention and improvement of hypertension." (PMID 38611371, 2024). "In the control group all 35 subjects with hypertension used ACE inhibitors." (PMID 38124483, 2024). "Due to its significant role in hypertension, inhibiting ACE is a well established clinical target." (PMID 39595018, 2024). "However, F. pinicola extract which was the best in ACE inhibition expressed almost 100 times weaker inhibition potential compared to the captopril (0.006 mg mL−1), often applied for the treatment of hypertension." (PMID 38257227, 2024). "Interestingly, it reduces the Firmicutes to Bacteroidetes ratio and the expression of angiotensin-converting enzyme (ACE) to prevent metabolic-related hypertension." (PMID 38397881, 2024). "Captopril is a widely used ACE inhibitor with a well-documented therapeutic profile, and finding a natural compound with comparable activity underscores the value of exploring plant-derived substances for hypertension management." (PMID 39771606, 2024). "ACE inhibitors are medications mainly used to treat and manage hypertension." (PMID 38333456, 2024). "Additionally, by blocking ACE, fasidotril decreases the production of Ang II, mitigating its vasoconstrictive and pro-inflammatory actions, and offering therapeutic benefits for hypertension and myocardial infarction." (PMID 39764460, 2024). "Drug-induced vasculitis can have catastrophic consequences and we recommend treating hypertension with first-line antihypertensives such as thiazide diuretics, angiotensin-converting enzyme (ACE) inhibitors or angiotensin II receptor blockers (ARBs), and dihydropyridine calcium-channel blockers." (PMID 39398788, 2024). "The efficacy of ACE inhibitors for the treatment of hypertension is widely recognized." (PMID 39275290, 2024). "Another consideration regarding eosinophilia in patients with hypertension may be the side effects of angiotensin-converting enzyme inhibitors (ACE inhibitors), one of the most common hypertension drugs." (PMID 38254726, 2024). "Consequently, the inhibition of ACE emerges as a significant therapeutic approach for the management of hypertension." (PMID 38540933, 2024). "The high penetrance of the DD genotype in African populations could explain why ACE inhibitors are ineffective first-line treatments among Africans resulting in more resistant forms of hypertension compared to other races." (PMID 39666621, 2024). "Furthermore, the efficacy of captopril in reducing hypertension and angiotensin-converting enzyme (ACE) in rodents was improved through the combination of captopril with garlic and its bioactive component, alliin." (PMID 38915405, 2024). "Therefore, research on natural ACE inhibitors is essential to mitigate these side effects and holds potential as both a preventive measure and complementary therapy for hypertension." (PMID 39598284, 2024). "Angiotensin-Converting Enzyme (ACE) is a key enzyme behind hypertension." (PMID 39834364, 2024). "Also, some of the patients were treated for hypertension (17.3%) and arrhythmias (13.7%) with beta-blockers and ACE inhibitors." (PMID 38667436, 2024). "Angiotensin-converting enzyme (ACE) is an enzyme that is part of RAS and is involved in the production of Angiotensin II; high levels of Angiotensin II cause arterial stiffness and structural remodeling, which lead to hypertension and enlarged PVS." (PMID 39610697, 2024).
Hypertension (continued). "TNF-α may contribute to hypertension by increasing the synthesis of angiotensin-converting enzyme (ACE)." (PMID 38672199, 2024). "Similarly, excessive angiotensin-converting enzyme (ACE) activity promotes vascular remodeling, high blood pressure, and chronic vascular inflammation by raising the levels of angiotensin II (Ang II)." (PMID 39517211, 2024). "Blocking the renin–angiotensin–aldosterone system (RAAS) with angiotensin-converting enzyme (ACE) inhibitors and angiotensin II type 1 receptor blockers decreases high blood pressure and reduces morbidity and mortality in patients with chronic heart failure and chronic kidney disease." (PMID 38255922, 2024). "ACE inhibitors are commonly used for the treatment of hypertension." (PMID 37888091, 2023). "Angiotensin-converting enzyme (ACE) is the key enzyme related to hypertension." (PMID 36839313, 2023). "Angiotensin I-converting enzyme (ACE) inhibitors are widely used to treat hypertension." (PMID 38139380, 2023). "A major, metabolic step in the pathophysiology of hypertension is the reaction catalyzed by ACE." (PMID 37822725, 2023). "Inhibition of ACE activity is a therapeutic alternative for the control of hypertension." (PMID 37241977, 2023). "The presence of ACE as an intracellular component or released by activated cells highlights its local or systemic role as a modulator of inflammatory immune responses during hypertension." (PMID 37854465, 2023). "Biopeptides or ACE-inhibitory peptides derived from fish proteins are often made under controlled circumstances by proteolyzing marine proteins advanced for the treatment of hypertension." (PMID 36976242, 2023). "Various commercially available antihypertensive drugs, including beta-blockers, angiotensin I-converting enzyme (ACE) inhibitors and calcium channel blockers, have been used to mitigate hypertension by inhibiting key enzymes and proteins involved in blood pressure regulation." (PMID 38126063, 2023). "The peptide KYIPIQ purified from yak milk casein has strong ACE inhibitory activity and may serve as a source of therapeutic drugs for hypertension." (PMID 37297335, 2023). "Therefore, studies are focusing on using natural resources as potential ACE-inhibitory agents against hypertension." (PMID 37446242, 2023). "Angiotensin-converting enzyme (ACE) can inactivate the vasodilator bradykinin to up-regulate blood pressure via modifying angiotensin (Ang) I to active Ang II, then inhibition of ACE activity is a crucial approach to mediate systematic hypertension." (PMID 37502715, 2023). "In this study, we demonstrated that endothelial-specific Sp1/Sp3 deletion resulted in endothelial dysfunction and hypertension, and that captopril, an ACE inhibitor and traditional antihypertensive drug, exerted part of its pharmacological effect by modulating Sp1/Sp3 levels in endothelial cells." (PMID 37735515, 2023). "Angiotensin-converting enzyme (ACE) polymorphism has been associated with various heart-related and other diseases such as atherosclerosis, myocardial infarction, ischemic stroke, and hypertension." (PMID 36916970, 2023). "The use of other treatments, including statins to control hyperlipidemia and ACE inhibitors/ARBs or beta blockers for the management of arterial hypertension, also increased with increasing age, most likely reflecting the increasing occurrence of multimorbidity in older patients." (PMID 37629262, 2023). "Treatment with both angiotensin-converting enzyme (ACE) inhibitors and angiotensin receptor blockers (ARBs) for hypertension is not recommended because it is linked with a higher incidence of major kidney adverse events (Class III, LoE A)." (PMID 37762932, 2023). "In particular, hypertension is treated with angiotensin-converting enzyme (ACE) inhibitors." (PMID 37299466, 2023).
Hypertension (continued). "Therefore, ACE inhibition has become an interesting target control for hypertension, a common progressive disorder leading to several chronic diseases such as cardiovascular disease, stroke, and renal disease." (PMID 37371891, 2023). "However, even after strict lipid and hypertension control with statins, angiotensin-converting enzyme (ACE) inhibitors, and angiotensin receptor blockers (ARBs), cardiovascular event rates have not dropped precipitously." (PMID 37174697, 2023). "ACE inhibitors are used in the management and treatment of hypertension." (PMID 38222129, 2023). "ACE inhibitors are medications generally indicated for hypertension." (PMID 37553559, 2023). "Thus, present study identified a novel potent ACE inhibitory peptide from moth bean that can be incorporated in a functional dietary formulation for regulation of hypertension." (PMID 37360301, 2023). "In this study, we identified fosinopril, a phosphonate-containing, FDA-approved angiotensin converting enzyme (ACE) inhibitor commonly used as a prodrug for hypertension and heart failure, as a potent inhibitor of Babesia duncani parasite development within human erythrocytes." (PMID 37797695, 2023). "Although the effect of antihypertensive drugs on COVID-19 patients with hypertension is controversial, the upregulation of ACE2 by ACE-inhibitors was linked to a dampened hyperinflammation and increased intrinsic antiviral responses of the cell in hypertensive COVID-19 patients." (PMID 37803348, 2023). "The ACE-1 inhibitory activity of the synthesized peptides is greater than the value reported for the L. digitata hydrolysate and shows the potential of these peptides for potential use in the treatment of hypertension." (PMID 36827131, 2023). "From our review, we can safely conclude that commercially available synthetic ACE inhibitors pose numerous side effects in patients, and since hypertension is a chronic disease and leads to various cardiovascular disorders, the long-term consumption of these synthetic inhibitors can be harmful." (PMID 37389408, 2023). "Therefore, bioactive peptides from natural sources such as animal products, plants, marine resources, microorganisms, and their fermentation products become safe and effective ACE inhibitors to treat hypertension." (PMID 37761189, 2023). "Introducing eight Trp into rabbit skeletal muscle protein (no Trp in wide sequence) endowed the protein with a more than 90% ACE inhibition rate, further suggesting that meat with a high content of Trp could have potential utility in hypertension regulation." (PMID 37107368, 2023). "Renin–angiotensin–aldosterone system (RAAS) blockade, achieved through use of ACE inhibitors and angiotensin-II receptor blockers (ARBs), can reduce systolic BP, comparable to that achieved by calcium-channel blockers (CCBs) in HD patients with hypertension." (PMID 37672130, 2023). "Thus, rapid screening methods for discovering ACE inhibitory peptides for novel hypertension therapeutics are in high demand." (PMID 37049880, 2023). "Paradoxically, though the ACE D allele is associated with the risk of cardiovascular disease (CVD), hypertension, Alzheimer’s disease, and other common causes of death in older people, a previous study noted an increased frequency of the DD genotype among a group of centenarians from France." (PMID 36834822, 2023). "Angiotensin-converting enzyme (ACE) is a target of hypertension treatment." (PMID 37908979, 2023). "Specific peptides from both MAP30 and Momordin, that have been shown to reduce hypertension in a rat model and to competitively inhibit angiotensin-converting enzyme (ACE), a homolog of ACE2 and the key receptor for SARS-CoV-2, have the potential to block viral entry." (PMID 37384752, 2023). "Therefore, the use of natural components, such as bioactive legume peptides, to suppress ACE activity has been implemented in studies on cardiovascular problems, particularly hypertension." (PMID 36985395, 2023).